ROR1 (ROR family WNT receptor 1)
Diseases named in the same sentence as ROR1 in open-access papers (continued):
Sharing a sentence is not in itself a finding about the gene and the disease.
glioma (6 papers, 2016 to 2026). A benign or malignant brain and spinal cord tumor that arises from glial cells (astrocytes, oligodendrocytes, ependymal cells). "Thus, in contrast to its role in other types of cancer, IGFBP5 may serve as an oncogene by activating ROR1/HER2-CREB signaling axis in glioma." (PMID 36949068, 2023). "For example, HIF1α is involved in promoting radioresistance by modulating AMPK-mediated ATM expression, promoting glioma invasion and stem cell formation via regulating MIR210HG and OCT1, and activating Ror1 transcription to influence cancer progression." (PMID 38893207, 2024). "RMPAhigh gliomas were also enriched in the expression of ERBB2, FGFR1 and MET (and its ligand HGF), DDR2 (a receptor for activated collagen fibers), as well as the WNT co-receptors ROR1 and RYK." (PMID 27385209, 2016).
breast tumor (5 papers, 2012 to 2022). "ROR1 has been associated with the CSC phenotype in several malignancies such as leukemia, ovarian and breast tumors." (PMID 31382410, 2019). "As expected, higher ROR1 expression was shown in the breast tumor tissue compared to normal tissue, validating that the antibody we used can specifically detect ROR1 expression." (PMID 28427197, 2017). "The breast tumors were reported to express high level of ROR1 when compared with their adjacent normal tissues." (PMID 28427197, 2017). "Therefore, we used breast tumors as positive controls to verify the specificity of ROR1 antibody." (PMID 28427197, 2017). "Finally, we examined paraffin-embedded primary human breast tumor tissues for ROR1 and p-CREB, and scored them on the basis of their intensity of staining for ROR1 or p-CREB." (PMID 22403610, 2012). "Across all breast tumor samples in the TCGA, ROR1 did not significantly predict survival with a hazard ratio of 1.33 (p = 0.14), but confirmed the highest ROR1 expression in BLBC compared to other molecular subtypes (n = 821 with molecular subtype designations)." (PMID 31137681, 2019).
colon carcinoma (5 papers, 2010 to 2024). "Our screening result identified HT-29 colon cancer cells having the highest Ror1 mRNA expression level." (PMID 20587074, 2010). "Similarly, cancer-related markers, such as ROR1 or EpCAM, which are overexpressed in PCa, but also in other carcinomas such as colon cancer, were not able to distinguish between the benign and malignant changes in the prostate." (PMID 35740652, 2022).
follicular lymphoma (5 papers, 2017 to 2024). Follicular lymphoma is a form of non-Hodgkin lymphoma characterized by a proliferation of B cells whose nodular structure of follicular architecture is preserved. "An association was described between hypomethylation of CD7 promoter region and its increased expression The orphan receptor tyrosine kinase ROR1 was shown to be expressed in follicular lymphoma." (PMID 28637510, 2017).
bladder cancer (4 papers, 2020 to 2025). "Furthermore, the results from immunohistochemistry clearly show the significance of using anti-ROR1 antibody as an additional diagnostic marker in patients with bladder carcinoma." (PMID 32695279, 2020). "ROR1 expression in bladder cancer cells (5637 and EJ138) was also examined by immunocytochemistry verifying the flow cytometry results." (PMID 32695279, 2020). "The immunocytochemistry and immunohistochemistry staining results also confirmed the presence of ROR1 on the surface of both bladder cancer cells and tissues, respectively." (PMID 32695279, 2020). "The aim of this study was to evaluate ROR1 cell surface expression in bladder cancer cells using a murine anti-ROR1 monoclonal antibody (mAb) called 5F1-B10 as well as investigate its potential in apoptosis induction." (PMID 32695279, 2020). "The expression of ROR1 in both bladder cancer cell lines was confirmed by immunofluorescence staining." (PMID 32695279, 2020). "Taken together, our findings indicate the critical role of ROR1 in bladder cancer cell survival and suggest this receptor as a promising target for development of novel therapeutic agents against bladder cancer cells." (PMID 32695279, 2020). "Immunohistochemical staining of human bladder carcinoma and normal bladder tissues also revealed a high level of ROR1 expression in the bladder carcinoma tissue in comparison with normal tissue." (PMID 32695279, 2020). "Taken together, our finding indicates the role of ROR1 in bladder cancer cell survival and suggests this receptor might be a promising target for developing novel therapeutic agents against bladder carcinoma." (PMID 32695279, 2020). "Our ROR1 antibody alone is also inducing apoptosis of bladder cancer cells." (PMID 32695279, 2020). "Therefore, a noninvasive diagnostic as well as a monitoring method using urine samples from patients with bladder cancer employing anti-ROR1 antibody in flow cytometry technique is recommended." (PMID 32695279, 2020). "This may suggest that ROR1 plays a role in the epigenetic silencing of CREB3L1 in TNBC and potentially in bladder cancer as well." (PMID 40427627, 2025). "Further in vivo studies is needed using a mouse model of human bladder carcinoma lacking cellular immunity (e.g. nude mouse) to apply only anti-ROR1 monoclonal antibody to draw such conclusion." (PMID 32695279, 2020). "ROR1 is not a bladder cancer specific marker and expressed in many other cancers 17,22,29,33,36,37." (PMID 32695279, 2020). "This may indicate there is no alternative signaling pathway to compensate lack of ROR1 in cell survival of bladder cancer cells." (PMID 32695279, 2020). "So far, no functional role of ROR1 in bladder carcinoma cell lines has been reported." (PMID 32695279, 2020). "This implies that ROR1 might be the only survival factor in bladder carcinoma and this could be the reason for not identifying so many targets for targeted therapy of this cancer." (PMID 32695279, 2020).
hepatocellular carcinoma (4 papers, 2019 to 2023). A malignant tumor that arises from hepatocytes. "In this study, we showed that ROR1 protein is overexpressed in hepatocellular carcinoma-derived cells from both mice and humans." (PMID 30832318, 2019). "For instance, when discussing ROR1 and EMT, the special case of hepatocellular carcinoma should be mentioned, since in that tumor entity ROR1 was associated more with an epithelial rather than a mesenchymal phenotype indicating that it might play an opposing role here." (PMID 33445713, 2021).
non-Hodgkin lymphoma (4 papers, 2014 to 2025). Distinct from Hodgkin lymphoma both morphologically and biologically, non-Hodgkin lymphoma (NHL) is characterized by the absence of Reed-Sternberg cells, can occur at any age, and usually presents as a localized or generalized lymphadenopathy associated with fever and weight loss. "Since the discovery of the elevated expression of ROR1 in CLL, increased levels of ROR1 have been described in a variety of hematological malignancies, including acute lymphocytic leukemia (ALL), non-Hodgkin lymphomas (NHL), and myeloid malignancies." (PMID 24752542, 2014).
B-cell acute lymphoblastic leukemia (3 papers, 2010 to 2022). A neoplasm of lymphoblasts committed to the B-cell lineage, typically composed of small to medium-sized blast cells. "ROR1 is overexpressed in various neoplasms, including different subsets of B-cell acute lymphoblastic leukemia and the cervical carcinoma Hela cells." (PMID 20686606, 2010). "Moreover, other Wnt ligands have been shown to interact with either ROR1 or ROR2 in various cellular contexts, such as Wnt16–ROR1 interaction in TCF3-PBX1 B-cell acute lymphoblastic leukemia and Wnt9a–ROR2 interaction during skeletal development." (PMID 31382410, 2019).
cervical carcinoma (3 papers, 2010 to 2022). A carcinoma arising from either the exocervical squamous epithelium or the endocervical glandular epithelium. "siROR1 treatment also significantly reduced CAV1 in A431 (vulval epidermoid carcinoma) and HeLa (cervical cancer) cell lines, indicating the involvement of ROR1 in other types of cancer cells." (PMID 26725982, 2016).
gynecological cancers (3 papers, 2022 to 2025). "Understanding the complex role of ROR1 expression and its downstream signaling is critical to the improvement of traditional and combinatorial therapies for patients with gynecological cancers." (PMID 40869147, 2025). "Given its critical role in resistance, self-renewal, and stemness, ROR1 offers a promising therapeutic target in gynecological cancers." (PMID 40869147, 2025). "Characterized by a paucity of expression in adult tissues yet overexpressed in multiple malignancies, receptor tyrosine kinase-like orphan receptor 1 (ROR1) has emerged as a target of interest in precision medicine, including gynecological cancers." (PMID 41415567, 2025).
hairy cell leukemia (3 papers, 2017 to 2024). Hairy cell leukemia (HCL) is a rare type of leukemia in which abnormal B-lymphocytes are present in the bone marrow, spleen and peripheral blood. "Importantly, ROR1 expression has been identified in lymphoid malignancies derived from mature B lymphocytes including CLL/SLL, hairy cell leukemia (HCL), MCL, DLBCL, and follicular lymphoma (FL)." (PMID 38638855, 2024).
mesothelioma (3 papers, 2019 to 2025). A usually malignant and aggressive neoplasm of the mesothelium which is often associated with exposure to asbestos. "The average percentage of ROR1 expression in tumoral cells was 68.3% (range 0–100%), and the average H-score was 143.08 (range 0–286, median 146) for all mesothelioma histologic variants combined." (PMID 38791952, 2024). "The sarcomatoid variant case showed higher ROR1 expression than the other mesothelioma variants." (PMID 38791952, 2024). "This is consistent with recent data indicating that many tumor types have low prevalence of ROR1 expression, whereas in some others, such as mesothelioma, it is more frequent." (PMID 40762544, 2025). "We found significant ROR1 expression in several tumor types, including mesothelioma, liposarcoma, GISTs, and endometrioid uterine carcinoma." (PMID 38791952, 2024). "A high prevalence of ROR1 expression was found in mesothelioma (84.6%), liposarcoma (36.1%), gastrointestinal stromal tumors (33.3%), and uterine endometrioid carcinoma (28.9%)." (PMID 38791952, 2024). "Further, mesothelioma exhibited frequent and high levels of ROR1 expression, which represents a previously unrecognized therapeutic opportunity." (PMID 38791952, 2024). "In our study, we found that the prevalence of ROR1 expression was low in most tumor types; however, a few tumor types, most notably mesothelioma, showed a large percentage of cancer cells expressed ROR1 and had a relatively high intensity of ROR1 expression." (PMID 38791952, 2024). "We found that 84.6% of mesothelioma tumors studied were positive for expression of ROR1 when any expression was considered (cut-off > 1)." (PMID 38791952, 2024). "Importantly, we have found clinically meaningful ROR1 expression—highly frequent and moderately intense ROR1 expression—in mesothelioma and moderately frequent and lower intensity ROR1 expression—in liposarcoma." (PMID 38791952, 2024). "Notably, high ROR1 prevalence was observed in mesothelioma, liposarcoma, gastrointestinal stromal tumors, and uterine endometrioid carcinoma." (PMID 38791952, 2024). "Our findings confirm this and suggest that ROR1 may be a novel therapeutic target for mesothelioma." (PMID 38791952, 2024).
multiple myeloma (3 papers, 2010 to 2017). "A ROR1-cFab prokaryotic expression vector was constructed from positive fusion cells (splenocytes from mice with high ROR1 immune titers were fused with myeloma cells) after three rounds of sub-clone affinity screening." (PMID 29212222, 2017). "To test the hypothesis that Stat3 activates ROR1, we used the multiple myeloma cell line MM1." (PMID 20686606, 2010). "Our group also constructed a ROR1 CAR in the SB transposon and showed unexpectedly that ROR1 CAR T cells were cytotoxic against both RPMI8226 multiple myeloma and SaOS2 OS cell lines (data not shown)." (PMID 26173023, 2015).
pancreatic adenocarcinoma (3 papers, 2015 to 2021). "A separate study (using a separate C-terminus targeting monoclonal antibody) detected ROR1 protein at low levels in 15% of pancreatic adenocarcinoma samples (n = 38)." (PMID 34763666, 2021).
Richter syndrome (3 papers, 2020 to 2024). Transformation of chronic lymphocytic leukemia into aggressive non-Hodgkin's lymphoma, usually diffuse large B-cell lymphoma (immunoblastic or centroblastic variant). "Our group has developed a ROR1 antibody conjugated to MMAE that was effective in a Richter’s syndrome mouse model." (PMID 38408999, 2024). "ROR1 expression was more frequently observed in primary refractory DLBCL (7/11, 83%), Richter ́s syndrome (9/10, 90%) and transformed follicular lymphoma (9/11, 82%) than in relapsed (8/22, 36%) and non-relapsed DLBCL patients (10/30, 33%) (p < 0.001)." (PMID 32586008, 2020). "Given these limitations, ROR1 expression in DLBCL was often observed in poor prognosis subgroups, such as primary refractory de novo DLBCL and Richter’s syndrome with the lowest frequency observed in non-relapsed DLBCL." (PMID 32586008, 2020). "ROR1 expression in tumor cells was more often observed in primary refractory DLBCL, Richter’s syndrome and transformed follicular lymphoma than in relapsed and non-relapsed DLBCL patients (p < 0.001)." (PMID 32586008, 2020).
small cell carcinoma of the lung (3 papers, 2021 to 2024). "The ERK pathway, which is frequently mutated in malignancies, was also inactivated by ROR1 inhibition, which is in agreement with a report showing that ERK was dephosphorylated followed by treatment with KAN0441571C in small-cell lung cancer cells." (PMID 36297673, 2022). "We hypothesize that ROR1-targeted therapy is effective in small cell lung cancer and synergizes with therapeutic BCL2 inhibition." (PMID 34088900, 2021).
stomach adenocarcinoma (3 papers, 2019 to 2024). "In stomach adenocarcinoma, transcript variants ROR1-v3 and ROR1-v1 were equally expressed." (PMID 36289823, 2022). "No ROR1 expression was seen in mesenchymal chondrosarcoma, rhabdomyosarcoma, or gastric adenocarcinoma cases." (PMID 38791952, 2024).
B-cell precursor acute lymphoblastic leukemia (2 papers, 2023 to 2024). "Other Wnt proteins can also bind to ROR1, as seen in conditions such as B-cell precursor acute lymphoblastic leukemia (BCP-ALL) and CLL." (PMID 39551787, 2024).
deafness (2 papers, 2023 to 2024). An inherited or acquired condition characterized by the complete loss of the ability to hear from one or both ears. "In humans, the molecular basis of ROR1 missense mutation-caused inner ear anomalies and deafness are linked to NF-κB deficiency, and this pathway also protects cochlear hair cells from aminoglycoside-induced ototoxicity." (PMID 37062025, 2023).
ductal adenocarcinoma (2 papers, 2012 to 2019). "It was found that ROR1 (Receptor Tyrosine Kinase Like Orphan Receptor 1) was elevated in invasive ductal adenocarcinoma following chemotherapy." (PMID 31394796, 2019).
endometrioid adenocarcinoma (2 papers, 2018 to 2024). An adenocarcinoma characterized by the presence of malignant glandular epithelial cells resembling endometrial cells. "Among the 45 uterine endometrioid carcinoma cases, we found that 28.9% showed ROR1 expression, with an average total ROR1 positivity in tumor areas of 9.9% (range 0–100%) and an average H-score of 16.8 (range 0–246)." (PMID 38791952, 2024).
head and neck squamous cell carcinoma (2 papers, 2025). A squamous cell carcinoma that arises from any of the following anatomic sites: lip and oral cavity, nasal cavity, paranasal sinuses, pharynx, larynx, and salivary glands. "22.0405.aF, now named PBA-0405, has recently successfully completed a Phase 0 clinical trial (NCT06273852) as an early proof of concept in ROR1-positive patients with head and neck squamous cell carcinomas and soft tissue sarcomas." (PMID 41479906, 2025).
pancreatic ductal adenocarcinoma (2 papers, 2017 to 2021). An infiltrating adenocarcinoma that arises from the epithelial cells of the pancreas. "In a standard cell viability assay, unstimulated T cells were co-cultured with the ROR1 positive PANC1 pancreatic ductal adenocarcinoma cell line at a 1:1 effector:target ratio (E:T) in the presence of either ROR1 BiTE or control CD19 BiTE." (PMID 28811962, 2017). "The Wnt receptors ROR1 and ROR2 are generating increased interest as cancer therapeutic targets but remain understudied in pancreatic ductal adenocarcinoma (PDAC)." (PMID 34763666, 2021).
serous ovarian cancer (2 papers, 2015 to 2022). "The serous ovarian cancer cell line OVCAR3 was chosen for ROR2 knockdown assays due to its expression of both ROR1 and ROR2 at the mRNA and protein level." (PMID 26515598, 2015). "We performed the qRT-PCR analysis of TGFβ components (TGFB1, TGFB2, TGFBR1, TGFBR2), Wnt5A/ROR1/ROR2, and Hippo-related genes (YAP1, TAZ, CCN1, and CCN2) in serous ovarian cancer subtypes (LGSOC, HGSOC, BLSOC) compared to the normal ovary." (PMID 35053353, 2022).
T-cell lymphoma (2 papers, 2015 to 2024). "The murine T-cell lymphoma cell line EL4 did not express ROR1 but following genetic modification with a ROR1 transposon this cell line showed bright staining for ROR1." (PMID 26030772, 2015).
urothelial carcinoma (2 papers, 2024). A malignant neoplasm derived from the transitional epithelium of the urinary tract (urinary bladder, ureter, urethra, or renal pelvis). "We utilized a large dataset of urothelial carcinoma (UC) tumors to characterize non‐canonical WNT signaling through WNT5A, ROR1, ROR2, or FZD2 expression." (PMID 38558536, 2024). "The role of the WNT5A pathway (WNT5A, ROR1, ROR2, and FZD2) in the pathogenesis and progression of urothelial carcinoma (UC) has not been fully elucidated." (PMID 38558536, 2024).
acute leukemia (1 paper, 2015). A clonal (malignant) hematopoietic disorder with an acute onset, affecting the bone marrow and the peripheral blood. "Subsequently, ROR1 was described on some acute leukemias and solid tumors." (PMID 26030772, 2015).
allergic asthma (1 paper, 2025). A asthma with a basis in a pathological type I hypersensitivity reaction. "This study suggests that obese patients defined by BMI may promote the development of allergic asthma by influencing the expression of plasma proteins such as TPST1, ROR1, and DAPK1." (PMID 39893495, 2025). "The results of this study indicate that plasma proteins such as TPST1, ROR1, and DAPK1 may mediate the relationship between obesity and allergic asthma." (PMID 39893495, 2025).
Alport syndrome (1 paper, 2018). A rare renal disease characterized by glomerular nephropathy with hematuria progressing to end-stage renal disease (ESRD), frequently associated with sensorineural deafness, and occasionally with ocular anomalies. "The role of this lens capsule-like material in development of the ROR1+ micro-lenses could be further tested, e.g. by generating micro-lenses from hPSCs that have been derived from individuals known to develop lens capsule-related cataract, such as those with Alport syndrome." (PMID 29217756, 2018).
arteriosclerosis (1 paper, 2022). A vascular disorder characterized by thickening and hardening of the walls of the arteries. "In fact, Ror1 and Ror2 are implicated in age-related diseases, including tissue fibrosis, atherosclerosis (or arteriosclerosis), neurodegenerative diseases, and cancers." (PMID 35493090, 2022).
auditory neuropathy (1 paper, 2024). A hearing disorder characterized by impaired transmission of signals through the auditory nerve, resulting in mild to severe hearing loss and poor speech perception. "In epithelial patterning (CD−M5), Tmtc2, Hgf, and Ccdc50 were associated with NSHL and Ror1 with hearing loss and auditory neuropathy." (PMID 39684410, 2024).